SNORA9B (small nucleolar RNA, H/ACA box 9B)
Gene: Small nucleolar RNA gene on chromosome 12 (123,616,708 to 123,616,840, forward strand). Ensembl gene ENSG00000206897.
Gene Ontology:
Biological process: RNA processing
Cellular component: nucleolus
Homologues: Orthologues: chimpanzee SNORA9B (99% identical), macaque SNORA9B (96% identical), rabbit SNORA9B (88% identical). Paralogues in human: SNORA9 (92% identical).